HLA-DRB1 (major histocompatibility complex, class II, DR beta 1)
Diseases named in the same sentence as HLA-DRB1 in open-access papers (continued):
Sharing a sentence is not in itself a finding about the gene and the disease.
Arthritis (23 papers, 2007 to 2025). Inflammation of a joint. "Clostridium-like bacteria, particularly Clostridium innocuum, were found to be more prevalent in the gut microbiota of HLA-DRB1*0401 transgenic mice, which are susceptible to arthritis." (PMID 40507919, 2025). "SE-coding HLA-DRB1 alleles are associated with earlier onset of arthritis and more severe bone erosion." (PMID 28481943, 2017). "The decreased Barnesiella in IL1rn−/− mice is consistent with a previous study associating the abundance of Barnesiella with resistance to arthritis in HLA-DRB1*0402 mice." (PMID 28645307, 2017). "The reactivity to FN-Cit1035,1036 was compared with the HLA-DRB1 alleles of the 278 early arthritis patients." (PMID 22339947, 2012). "In this study, we have examined the relationship between HLA-DRB1 alleles and RA in an inception cohort of early arthritis patients, and we confirm previous evidence of an association between SE-containing HLA-DRB1 alleles and ACPA-positive RA." (PMID 20370905, 2010). "Additionally, HLA-DRB1*04:05 has been associated with ICI-induced arthritis and HLA-DRB1*11:01 with the development of pruritus or colitis during therapy." (PMID 38611115, 2024). "Furthermore, HLA-DRB1*04 showed significant association to LN and arthritis while HLA-DRB1*15 was significantly associated with oral ulcer in Malay SLE patients." (PMID 33644084, 2020). "Moreover, a humanized mouse model carrying the human RA susceptibility allele (“shared epitope”) HLA-DRB1*401 showed increased gut permeability prior to the induction of arthritis." (PMID 31292292, 2019). "Given the prior knowledge that there likely are arthritis risk loci other than HLA-DRB1 in the region, it appears the tests may have inadequate power to detect the presence of these loci in certain cases." (PMID 18466541, 2007). "Collagen II259–273 is the dominant epitope in the murine collagen-induced arthritis model in HLA-DRB1*04:01 or HLA-DRB1*01:01 transgenic mice and the collagen II259–273 specific TCR repertoire in these mice is highly restricted." (PMID 29403492, 2018). "Following on this hypothesis, Hill and Cairns developed a mouse model of arthritis by immunizing HLA-DRB1*0401 transgenic mice with citrullinated fibrinogen." (PMID 35432329, 2022). "Also, citrullinated fibrinogen induces arthritis in HLA-DRB1*0401 transgenic mice, and transfer of their splenic T cells causes arthritis to recipient mice." (PMID 29033912, 2017). "Using mice carrying the RA-resistant allele HLA-DRB1*0402 and the haplotype *0402/DQ8 in an arthritis model demonstrated that the DQ loci could be prominent in disease predisposition, while DR4 subtypes acted as modulators of inflammatory response and sex-specificity." (PMID 40005622, 2025). "Our association analysis demonstrated that the HLA-DRB1*04 allele in Malay SLE patients (with and without LN) was significantly associated with renal disorders and arthritis." (PMID 33644084, 2020). "Indeed, in humanized HLA-DRB1*0401 mice, which develop a spontaneous female sex-bias disease, age- and sex-driven differences in the gut-microbiota of non-arthritic control mice are lost following arthritis development." (PMID 35783625, 2022).
cervical cancer (21 papers, 2010 to 2025). A primary or metastatic malignant neoplasm involving the cervix. "We have tried to keep the focus on the rs9272143 variant concerning the progression of cervical cancer as HLA‐DRB1 expression is found in the cervix." (PMID 33586351, 2021). "A recent meta-analysis of 36 case-control studies (6645 cases and 9095 controls), revealed multiple HLA-DRB1 alleles associated with cervical cancer in women of diverse ancestry populations." (PMID 34683414, 2021). "Studies have reported that the haplotype HLA‐B*0702‐DRB1*1501/HLADQB1*0602 increases the risk of cervical carcinoma, whereas the haplotype HLA‐B*1501/HLA‐DRB1*1301/HLA‐DQA1*0103/HLA‐DQB1*0603 protects from the risk of the disease progression." (PMID 33586351, 2021). "Reduced risk of HPV18-associated cervical cancer was seen with HLA Class II alleles (HLA-DRB1*13 (OR = 0.51, P = 0.0058), HLA-DQB1*0603 (OR = 0.42, P = 0.021) and HLA-DQA1*0103 (OR = 0.50, P = 0.041))." (PMID 28806749, 2017). "Strong associations between HPV16 cervical cancer cases and amino acid positions 13 and 71 were found in HLA-DRB1 (P = 2.69 × 10−13 and 6.22 × 10−7 respectively), and position 156 in HLA-B (P = 4.93 × 10−8)." (PMID 28806749, 2017). "It is, hence, biologically plausible that carriers of the C allele of rs9272143, which have higher expression level of HLA-DRB1 are less susceptible to cervical cancer." (PMID 24403192, 2014). "Findings from published studies that have examined the association HLA-DRB1 alleles and the risk of cervical cancer have been inconsistent." (PMID 24551099, 2014). "More studies on individuals from various ethnic groups and large-scale and well designed case-control studies are needed to determine the role of HLA-DRB1 polymorphisms in the outcome of cervical cancer." (PMID 24551099, 2014). "In summary, in the present study we performed a meta- analysis on the association of cervical cancer with the HLA-DRB1 alleles." (PMID 24551099, 2014). "We found that the protective haplotype DRB1*1301-DQA1*0103-DQB1*0603 has a direct effect on cervical cancer and always occurs together with the C allele of a HLA-DRB1 cis-eQTL (rs9272143), which increases the expression of HLA-DRB1." (PMID 24520070, 2014). "As many conflicting reports have been relatively small in sample size, we performed a meta-analysis that examined the association between HLA-DRB1 allele families and alleles and cervical cancer." (PMID 24551099, 2014). "When the six studies in Uighurs were analyzed separately, 5 of 13 HLA-DRB1 allele families were found to be significantly associated with cervical cancer." (PMID 24551099, 2014). "Meta-analysis of relationship between HLA-DRB1 allele polymorphism and cervical cancer in the Chinese Uighur population." (PMID 24551099, 2014). "Several studies have reported a positive relation between HLA-DRB1 alleles and cervical cancer, but findings in different ethnic population have been controversia." (PMID 24551099, 2014). "Our results indicated the difference of HLA-DRB1 genetic susceptibility of cervical cancer in Chinese population." (PMID 24551099, 2014). "Susceptibility to HPV infection or cervical cancer and precancerous lesion development was associated with the HLA class II: HLA-DRB1 alleles; HLA-DQB1 alleles; HLA-DPB1 alleles; and classes I and II haplotypes." (PMID 23936772, 2013). "Due to its high genetic variability, essential role in antigen presentation, and consequent involvement, in mediating the immune response, numerous studies have investigated the association between HLA class II loci and cervical cancer, mainly exploring HLA‐DRB1 and HLA‐DQB1 genes." (PMID 40600436, 2025). "In contrast, HLA‐DRB1*13:01 has been associated with lower risk of cervical cancer." (PMID 40600436, 2025).
cervical cancer (continued). "A recent meta-analysis found the class II alleles HLA-DQR*02, -*03, and -*06:03 to decrease and HLA-DQB1*05, -*03:01, and -*04:02 to increase risk of cervical cancer, while a genome-wide study concluded HLA-DRB1*06:02 and -*15:01 to be major risk alleles in cervical carcinogenesis." (PMID 35363864, 2022). "Considering HPV18-associated cervical cancer (n = 166 cases), association with increased risk was strongest with HLA-DRB1*15 (OR = 1.68, P = 0.0013) and HLA-DQB1*0602 (OR = 1.65, P = 0.0030), with only nominal HLA Class I risk associations seen with HLA-B*0702 and HLA-C*0702." (PMID 28806749, 2017). "The etiology of cervical cancers might be related to risk factors, and HLA-DRB1 gene polymorphism was initially proposed in the late 1990s and has created considerable interest." (PMID 24551099, 2014). "In a genome-wide association study, we have previously identified and performed the initial replication of three novel susceptibility loci for cervical cancer: rs9272143 upstream of HLA-DRB1, rs2516448 adjacent to MHC class I polypeptide-related sequence A gene (MICA), and rs3117027 at HLA-DPB2." (PMID 24403192, 2014). "Meta-analysis of associations between HLA-DRB1 alleles and cervical cancer." (PMID 24551099, 2014). "However, recent studies on the association between HLA-DRB1 allele polymorphisms and cervical cancer have been inconclusive and controversial." (PMID 24551099, 2014). "HPV infection type is connected with polymorphisms in HLA-DRB1 (rs77689370), which ultimately affects how quickly high-risk HPV-infected cervical lesions develop into invasive cervical cancer." (PMID 38455474, 2024). "GWAS with these three different novel variants (rs6726538 of INSIG2, rs9272143 of HLA‐DRB1, and rs7780883 of GCNT1P5) imposed the probability of cervical cancer progression." (PMID 33586351, 2021). "We have carried out this case‐control study to investigate the association of INSIG2 rs6726538 (A; T), HLA‐DRB1 rs9272143 (T; C), and GCNT1P5 rs7780883 (G; A) with cervical cancer." (PMID 33586351, 2021). "Our study found the association of INSIG2 rs6726538 (A; T), HLA‐DRB1 rs9272143 (T; C), and GCNT1P5 rs7780883 (G; A) polymorphisms with cervical cancer risk in the Bangladeshi population." (PMID 33586351, 2021). "Conversely, HLA-DRB1 specific alleles, including DRB1*04:01, DRB1*10:01, DRB1*11:01, DRB1*15:01 and DRB1*15:02 were associated with an increased risk of cervical cancer." (PMID 34683414, 2021). "Our study summarizes that INSIG2 rs6726538 (A; T), HLA‐DRB1 rs9272143 (T; C), and GCNT1P5 rs7780883 (G; A) polymorphisms are associated with cervical cancer development in the Bangladeshi population." (PMID 33586351, 2021). "SNP rs9272143 (T; C) is located in the class II region (major histocompatibility complex, MHC region) of chromosome 6 (p‐arm, 6p21.32) between HLA‐DRB1 and HLA‐DQB1 and associated with cervical cancer." (PMID 33586351, 2021). "The first GWAS of cervical cancer on mostly Swedish patients with cervical intraepithelial neoplasia (CIN) III revealed that rs2516448 C/T (near MICA), rs9272143 T/C (between HLA-DRB1 and DQA1), and rs3117027C/A (at HLA-DPB2) are associated with CIN III5." (PMID 30333560, 2018). "Considering amino acid associations of HPV18-associated cervical cancer, association was again seen with amino acid position 13 in HLA-DRB1 (P = 7.99 × 10−5), but only modest association with amino acid position 71 in HLA-DRB1 (P = 0.0019)." (PMID 28806749, 2017). "A total of 12 studies, including 3,410 cervical cancer cases and 1,735 healthy controls, were evaluated in the current meta-analysis, which addressed 38 HLA-DRB1 subtypes." (PMID 24551099, 2014). "Although the correlation of cervical cancer with HLA-DRB1 genes has been demonstrated by various studies, the mechanisms underlying the effect have yet to be elucidated." (PMID 24551099, 2014).
cervical cancer (continued). "There are some genetic association studies conducted on Bangladeshi Breast cancer and cervical cancer population to evaluate susceptible single nucleotide polymorphisms of INSIG2, HLA-DRB1, GCNT1P5, IL1β, IL4R, IL6, FGFR2, CYP1A1, ESR1 genes and disease outcome." (PMID 40920780, 2025). "Our study concludes that INSIG2 rs6726538, HLA‐DRB1 rs9272143, and GCNT1P5 rs7780883 polymorphisms may contribute to the development of cervical cancer in the Bangladeshi population." (PMID 33586351, 2021). "Another study conducted in Europe, including a total of 2866 cervical cancer cases and 6481 controls confirmed the strong association of the MHC with cervical neoplasia, and identified the amino acid positions 13 and 71 in HLA-DRB1 and 156 in HLA-B (within both HLA Class I and Class II alleles)." (PMID 34683414, 2021). "Controlling for amino acids 13 and 71 in HLA-DRB1 left no residual HLA Class II allele or amino acid associations with HPV16-associated cervical cancer (P > 0.001)." (PMID 28806749, 2017). "These charge differences at these keys position within pocket 4 of the HLA-DRB1 the peptide binding groove may interact with putative HPV peptides that are permissive for or protect against development of infections that lead to cervical cancer." (PMID 28806749, 2017). "Our study points to the importance of expression level of HLA-DRB1 in cervical carcinoma." (PMID 24403192, 2014). "Allele frequency of HLA-DRB1*14 was particularly reduced in patients with cancer when compared with the HPV–persistent group (p = 0.04), suggesting that this allele is a possible protective factor for the development of cervical cancer (OR = 2.98)." (PMID 24000898, 2013). "Specifically, three haplotypes, HLA-DRB1*15/HLA-DQB1*0602/HLA-DQA1*0102, HLA-B*0702/HLA-C*0702 and HLA-DRB1*0401/HLA-DQA1*0301, were associated with increased risk of both HPV16 and HPV18-associated cervical cancer, and for the development of both squamous cell carcinoma and adenocarcinoma." (PMID 34683414, 2021). "Overall, three haplotypes, HLA-DRB1*15/HLA-DQB1*0602/HLA-DQA1*0102, HLA-B*0702/HLA-C*0702, and HLA-DRB1*0401/HLA-DQA1*0301, were associated with increased risk of both HPV16 and HPV18-associated cervical cancer, and for the development of both squamous cell carcinoma and adenocarcinoma." (PMID 28806749, 2017). "Our results support the role of HLA-DRB1 and MICA in the pathogenesis of cervical cancer." (PMID 24403192, 2014).
leprosy (20 papers, 2009 to 2024). Leprosy is a chronic infectious disease affecting primarily the skin and peripheral nervous system. "Recent research indicates that the four amino acid polymorphisms in HLA-DRB1, HLA-B, and HLA-A were recently identified as key factors in the association of leprosy with HLA in Vietnamese cases." (PMID 38440733, 2024). "The HLA-DRB1*13 allele was discovered to be related to leprosy in the Liangshan Yi Autonomous Region of Sichuan Province." (PMID 36800375, 2023). "HLA-DRB1*15:01 has been identified as a dominant determinant of leprosy risk in Chinese populations, with confirmatory evidence of association in Vietnamese and Brazilian populations." (PMID 36121873, 2022). "HLA-DRB1*15 has been identified as one of the most remarkable risk alleles in a genome-wide association study about leprosy in China." (PMID 35769990, 2022). "For example, HLA-DRB1*15 has been shown to be an allele linked to leprosy susceptibility in Indian and Brazilian populations and also has been associated with an increased leprosy risk in Chinese populations." (PMID 35769990, 2022). "In China, a genome-wide association study of leprosy showed that HLA-DRB1*15 was the most significant risk allele." (PMID 34976012, 2021). "The strongest leprosy susceptibility factors in our study were the HLA-DRB1*10:01 and HLA-DQA1*01:05 alleles which are in complete LD in the Vietnamese population." (PMID 32776973, 2020). "An allele that needs to be considered is HLA-DRB1*04:05 which was associated with protection from leprosy in the present as well as other studies." (PMID 32776973, 2020). "For this, we adjusted each of the formally non-significant HLA alleles on the presence of HLA-DQA1*01:05, HLA-C*07:06 and HLA-DRB1*12 and identified seven HLA four-digit alleles with evidence (Pconditional < 0.01) for association with leprosy." (PMID 32776973, 2020). "Several studies have consistently reported the involvement of HLA class II alleles, mostly HLA-DRB1 alleles, as key genetic factors controlling susceptibility to various forms of leprosy." (PMID 32421744, 2020). "Previous studies in large, well powered samples of Chinese leprosy patients had identified HLA-DRB1*15:01 as the strongest leprosy associated HLA allele (OR = 2.17, P = 4.21 × 10−44)." (PMID 32776973, 2020). "Taken together, these results implicated HLA-DRB1*10:01/ HLA-DQA1*01:05 and HLA-DRB1*15:01 as strong global leprosy risk factors." (PMID 32776973, 2020). "The univariable borderline association of HLA-DRB1*07:01 with leprosy was fully explained by HLA-C*07:06/HLA-B*44:03 by multivariable analysis." (PMID 32776973, 2020). "Taken together the combined results of the present and previous studies strongly support the role of HLA-DRB1*10:01~ HLA-DQA1*01:05 as major leprosy risk factor in independent Indian and Vietnamese samples." (PMID 32776973, 2020). "The leprosy protective signal #2 is dominated by alleles that are part of a HLA-C*07:06 ~ HLA-B*44:03 ~ HLA-DRB1*07:01 haplotype." (PMID 32776973, 2020). "We performed a comparative analysis of the alleles that were previously reported to be associated with the polar forms of leprosy (HLA-DRB1*15, HLA-DRB1*16, and HLA-DRB1*03 for TT and HLA-DQB1*05 and HLA-DQB1*06 for LL) by direct counting." (PMID 25605482, 2015). "In B leprosy patients, we observed decreased frequencies for these 2 alleles (5.94% for HLA-C*05 and 16.34% for HLA-DRB1*07)." (PMID 25605482, 2015). "Amino acid residues involved in the peptide binding groove of HLA-DRB1 alleles were examined in three Nigerian ethnic groups (Bini/Igbo, Yoruba, and Efik) with leprosy." (PMID 23936864, 2013). "In this gene-centric microarray study, we have genotyped SNPs in over 2,000 genes and identified TLR1 and HLA-DRB1/DQA1 as major leprosy susceptibility genes." (PMID 20617178, 2010). "The effect sizes of these associations suggest that TLR1 and HLA-DRB1/DQA1 are major susceptibility genes in susceptibility to leprosy." (PMID 20617178, 2010).